BRCA2 (BRCA2 DNA repair associated)
Diseases named in the same sentence as BRCA2 in open-access papers (continued):
Sharing a sentence is not in itself a finding about the gene and the disease.
prostate carcinoma (continued). "In men under 65 years of age, carriers of mutated BRCA1 have a 1.8 fold increased risk of prostate cancer and BRCA2 carriers an 8.6 fold increased risk." (PMID 28946846, 2017). "Our meta-analysis showed that a BRCA2 mutation predicted poor survival outcomes in patients with prostate cancer, especially in those undergoing treatments with radiotherapy." (PMID 28410213, 2017). "There are certain similarities as well as dissimilarities between BRCA2-mutated prostate cancer and other tumor entities in which HR defects occur at a sizable proportion such as triple negative breast cancer (TNBC)." (PMID 28676659, 2017). "In the present study, we detected BRCA2 mutations in approximately 15% patients with primary metastatic or localized high-risk prostate cancer who subsequently developed castration resistance and were treated with docetaxel." (PMID 28676659, 2017). "In a recent somatic sequencing study of castration resistant prostate cancer the germline BRCA2 mutation rate was shown to be as high as 12.7%." (PMID 28031937, 2016). "We have recently evaluated the contribution of the germline BRCA1/BRCA2 founder mutations for early-onset and/or familial prostate cancer in Portugal." (PMID 27532258, 2016). "Findings concluded that germline mutations in BRCA2 are an independent prognostic factor for survival in prostate cancer." (PMID 26236408, 2015). "BRCA2 alterations are less common, but those with germline BRCA2 alterations are known to be at high risk of prostate cancer diagnosis and high risk of having aggressive disease." (PMID 26258074, 2015). "Previously, an increased incidence was reported in men with BRCA2 mutations and prostate cancer that were diagnosed before 65 years." (PMID 26236408, 2015). "It was calculated that BRCA2 mutations amount for approximately 6 % of the increased familial risk of prostate cancer." (PMID 26236408, 2015). "Assuming that LOH occurs only because the cancer is caused by the germline mutation, carriers of BRCA2 mutations are at 3.5-fold increased risk of prostate cancer." (PMID 26433958, 2015). "As with prostate cancer incidence, it has been suggested that patients with pancreatic cancer and germline BRCA2 mutations tend to be of Ashkenazi Jewish decent and have a younger than average age of onset." (PMID 26236408, 2015). "These authors found that the prostate cancer outlier lncRNA PCAT-1 can regulate the cellular response to genotoxins by repressing the expression of BRCA2 to create a deficiency in homologous recombination (HR)." (PMID 26110379, 2015). "It was reported that 50 % of the six prostate cancer patients carrying BRCA2 mutations were diagnosed before aged 50 years." (PMID 26236408, 2015). "Several studies indicate that male carriers of BRCA2 are at an increased risk of developing prostate cancer while men with a BRCA1 mutation are believed to have a slightly higher risk of developing prostate cancer than those who possess no BRCA1/2 mutations." (PMID 26236408, 2015). "A recent report on castrate-resistant prostate cancer found that 7% of cases have missense or truncating mutations in BRCA2, and an additional 12% have alterations in other DNA repair/recombination genes associated with response to PARP inhibitors." (PMID 26258074, 2015). "BRCA2 mutations are also associated with increased risks in men for prostate cancer and pancreatic cancer, and possibly increased risks for gallbladder, stomach cancer and melanoma." (PMID 25632310, 2015). "Results showed that BRCA2 mutation carriers had a 3.2-fold increased risk of high grade prostate cancer." (PMID 26236408, 2015). "This suggests that while associations have been established, the overall contribution of BRCA2 mutations to the familial aggregation of prostate cancer is small." (PMID 26236408, 2015). "As with prostate cancer, it has been suggested that pancreatic cancer patients who possess a mutated BRCA2 gene have a younger age of onset." (PMID 26236408, 2015).
prostate carcinoma (continued). "Another study showed that two of 290 participants with prostate cancer possessed germline protein-truncating BRCA2 mutations, giving an overall prevalence of 0.69 %." (PMID 26236408, 2015). "For BRCA2 mutation carriers, the relative risk of developing prostate cancer was estimated as 4.65, rising to 7.33 for men younger than 65 years." (PMID 26433958, 2015). "Many research groups have reported that BRCA1 and BRCA2 mutation carriers are more likely to develop a more aggressive prostate cancer phenotype, generally associated with a higher probability of nodal involvement, distant metastasis, and low grade tumours." (PMID 24660075, 2014). "The results from the Breast Cancer Linkage Consortium (BCLC) showed a RR of 4.65 of prostate cancer in male BRCA2 mutation carriers (RR 7.33 below the age of 65 years) and 1.07 in BRCA1 carriers (with a RR of 1.82 for men under 65 years old)." (PMID 25047061, 2014). "There was an approximately equal division of men between BRCA1 mutation carriers, BRCA2 mutation carriers and controls; 21 men had prostate cancer." (PMID 24489760, 2014). "Of the 240 BRCA1 mutation carriers, 5 developed prostate cancer, and of the 207 BRCA2 mutation carriers, 16 individuals were diagnosed." (PMID 24489760, 2014). "On the other hand, mutations in BRCA2 have been reproducibly associated with prostate cancer risk, but their frequency is low in prostate cancer families." (PMID 23064873, 2013). "The BRCA2 mutation contributing to the young-onset prostate cancer has shown to be related to the Fanconi anemia pathway and DNA repair processes." (PMID 24565337, 2013). "Men with germ line mutation of Tumor suppressor gene BRCA2 have a 20 fold increased risk of prostate cancer while the most common alteration in prostatic cancer is hypermethylation of glutathione S-trasferase (GSTP1) gene which down-regulates GSTP1 expression." (PMID 24063260, 2013). "Studies in prostate cancer have reported rare gene coding mutations in BRCA2 (found in 2% of cases <55 years) to be associated with greater risk of prostate cancer (RR>4.5) and more aggressive disease." (PMID 23555315, 2013). "Genes that increase susceptibility to both breast and prostate cancer have been observed previously; for example, BRCA2." (PMID 23190577, 2012). "In recent studies we and others have demonstrated the relative risk for developing prostate cancer in male BRCA2 mutation carriers as between 2.9 to 4.8 times the general population." (PMID 23146383, 2012). "Consistent with this, analysis of men with early-onset disease indicates that BRCA2 carriers account for between 0.8–2% of prostate cancer cases, compared with the prevalence of 0.1% BRCA2 mutations in the general population." (PMID 20585617, 2010). "BRCA2 has also been implicated in prostate cancer etiology, but it is unclear the impact that mutations in this gene have on prostate tumourigenesis." (PMID 20585617, 2010). "BRCA2 loss of function due to mutations is linked to poor survival in prostate cancer and rare germline mutations have been associated with early-onset of prostate cancer." (PMID 20805891, 2010). "Studies on human carriers of deleterious BRCA2 mutations have implicated this gene in prostate cancer etiology, but its function in this malignancy is unclear." (PMID 20585617, 2010). "To understand the role of Brca2 in prostate cancer we have used a prostate–specific Cre line and a conditional Brca2 allele to delete Brca2 in adult mouse prostate epithelia." (PMID 20585617, 2010). "There is an increased risk of prostate cancer in individuals carrying a mutation in BRCA2, particularly early-onset disease." (PMID 20585617, 2010). "The PARP inhibitor olaparib was recently evaluated in a phase I clinical trial and showed antitumour activity in BRCA1 or BRCA2 mutation carriers with ovarian, breast or prostate cancer." (PMID 19904273, 2009).
prostate carcinoma (continued). "Early studies in Iceland identified a BRCA2 founder mutation, 999del5, that segregates with prostate cancer particularly in cases diagnosed ≤ 65 years." (PMID 19476645, 2009). "We mutation screened all coding regions and intron/exon boundaries of the BRCA2 gene in the youngest prostate cancer case who carried the linked 13q segregating haplotype, as well as in a distantly related haplotype carrier to confirm any segregation." (PMID 19476645, 2009). "Our results are consistent with a growing pool of evidence that BRCA2 plays at most a minor role in causing prostate cancer in high-risk prostate cancer families." (PMID 19476645, 2009). "To further assess involvement of BRCA2 in familial prostate cancer, we screened for BRCA2 variants in high-risk prostate cancer pedigrees that showed at least nominal linkage to the BRCA2 region on chromosome 13q." (PMID 19476645, 2009). "There were 183 men with prostate cancer who were known or probable carriers of a BRCA2 mutation and 119 men with prostate cancer who were known or probable carriers of a BRCA1 mutation." (PMID 18577985, 2008). "We observed that men with prostate cancer and a BRCA2 mutation experienced relatively poor survival, in comparison to men with prostate cancer and a BRCA1 mutation." (PMID 18577985, 2008). "In this study, we examined survival for men with prostate cancer and a BRCA2 mutation, and compared this to a similar group of men with a BRCA1 mutation." (PMID 18577985, 2008). "Given that only one-half of the first-degree relatives are expected to be gene carriers, this corresponds to a relative risk of prostate cancer, given a BRCA2 mutation, of approximately five." (PMID 18577985, 2008). "Despite these numerous limitations, we believe that the differences observed in survival of the BRCA1 and BRCA2 carriers can be attributed to the adverse effect of the BRCA2 mutation on prostate cancer survival." (PMID 18577985, 2008). "We obtained the age at diagnosis, age at death or current age from 182 men with prostate cancer from families with a BRCA2 mutation and from 119 men with prostate cancer from families with a BRCA1 mutation." (PMID 18577985, 2008). "Prostate cancer is a clinical manifestation of the BRCA2 gene, but only a small proportion of prostate cancers are attributable to BRCA2 mutations." (PMID 18577985, 2008). "In conclusion, the results of this study indicate that germline protein-truncating mutations in the BRCA2 gene confer an elevated RR (almost eight-fold) of developing early-onset prostate cancer in Caucasian men." (PMID 17700570, 2007). "The estimated RR of developing prostate cancer by age 56 years from a deleterious germline BRCA2 mutation was 23.0 (95%CI 9.0–57.0)." (PMID 17700570, 2007). "As both disease-associated BRCA2 mutation carriers were Caucasian, the prevalence of such mutations in whites is 0.78% (95%CI 0.09–2.81%); the estimated RR of prostate cancer is 7.8 (95%CI 1.8–9.4) in Caucasian BRCA2 mutation carriers." (PMID 17700570, 2007). "The estimated cumulative risk (i.e. penetrance) of prostate cancer to age 55 years in Caucasian men due to carrying a disease-associated BRCA2 mutation is about 1.1%, and the population attributable risk of prostate cancer in this same group is 0.7%." (PMID 17700570, 2007). "BCLC family-based studies found that prostate cancer risk in BRCA2 carriers depend on age and BRCA2 mutation location." (PMID 17213823, 2007). "Studies of families who segregate BRCA2 mutations have found that men who carry disease-associated mutations have an increased risk of prostate cancer, particularly early-onset disease." (PMID 17700570, 2007). "A study of sporadic prostate cancer in the UK reported a prevalence of 2.3% for protein-truncating BRCA2 mutations among patients diagnosed at ages ⩽55 years, highlighting the potential importance of this gene in prostate cancer susceptibility." (PMID 17700570, 2007).
prostate carcinoma (continued). "Both cases were Caucasian, yielding a mutation prevalence of 0.78% (95% confidence interval (95%CI) 0.09–2.81%) and a relative risk (RR) of 7.8 (95%CI 1.8–9.4) for early-onset prostate cancer in white men carrying a protein-truncating BRCA2 mutation." (PMID 17700570, 2007). "When the analysis was stratified by the age at diagnosis, the RR of prostate cancer was 8.0 (95%CI 4.1–14.0) among protein-truncating BRCA2 mutation carriers diagnosed at ages <65 years." (PMID 17700570, 2007). "In that study, the two men with protein-truncating BRCA2 mutations were diagnosed with prostate cancer at ages ⩽56 years, and both had a brother with prostate cancer." (PMID 17700570, 2007). "The main goal of the current study was to determine the frequency of germline protein-truncating BRCA2 mutations in early-onset prostate cancer patients in a US population." (PMID 17700570, 2007). "Results suggest that protein-truncating BRCA2 mutations confer an elevated RR of early-onset prostate cancer." (PMID 17700570, 2007). "To date, only one study has assessed the contribution of BRCA2 mutations in early-onset sporadic prostate cancer." (PMID 17700570, 2007). "Although this represents a substantially elevated RR of earlier-onset prostate cancer associated with carrying a germline protein-truncating BRCA2 mutation, such mutations are very rare (∼0.1%) in the general US population." (PMID 17700570, 2007). "In this population-based study of 290 patients diagnosed with prostate cancer before age 55 years, there were two patients with germline protein-truncating BRCA2 mutations, yielding an overall prevalence of 0.69% (95%CI 0.08–2.49%)." (PMID 17700570, 2007). "The estimated RR of prostate cancer was 23.0 (95%CI 9.0–57.0) among protein-truncating BRCA2 mutation carriers in that study." (PMID 17700570, 2007). "Recent studies suggest that carriers of deleterious mutations of the BRCA2 gene have an increased prostate cancer risk." (PMID 15385056, 2004). "Several independent studies have demonstrated that individuals with germline mutations in BRCA2 are at increased risk of prostate cancer." (PMID 15280931, 2004). "The risk of prostate cancer is known to be elevated in carriers of germline mutations in BRCA2, and possibly also in carriers of BRCA1 and CHEK2 mutations." (PMID 15280931, 2004). "Such mutations would account for a small proportion of cases only but the increased risk of prostate cancer in male BRCA1 and BRCA2 mutation carriers indicates some commonality in histogenetic pathways in breast and prostate carcinomas." (PMID 11875732, 2002). "There was a significant difference in the incidence of the BRCA1 and BRCA2 mutations in the breast and prostate cancer cases (P = 0.05, two-tailed Fisher's exact test)." (PMID 9743298, 1998). "We tested for the BRCA1 185delAG frameshift mutation, found in 0.9% of Ashkenazi Jews, and the BRCA2 6174delT mutation, found in 1% of Ashkenazi Jews, in Ashkenazi Jewish men with prostate cancer." (PMID 9743298, 1998). "We observed that BRCA1 pathogenic variants affect prostate cancer aggressiveness such as BRCA2 pathogenic variants, and the first case of aggressive prostate cancer with a BRCA1 pathogenic variant had long-term survival through early detection and multidisciplinary treatment." (PMID 41423785, 2026). "BRCA1 pathogenic variants are associated with a lower risk of developing prostate cancer than BRCA2, but aggressiveness remains unclear." (PMID 41423785, 2026). "Additionally, BRCA2 mutations are linked to a 40% increased risk of prostate cancer and are detected in 0–17% of pancreatic cancer cases." (PMID 39985003, 2025). "BRCA1 and BRCA2 are associated with advanced prostate cancer progression and poor prognosis." (PMID 40725150, 2025).
prostate carcinoma (continued). "Compared with wild-type (WT) tumors, significantly more adaptive immune response cells, especially tumor-infiltrating lymphocytes (TILs), are enriched in BRCA1/2 mutant TNBC, as well as prostate cancer and pancreatic cancer with BRCA2, PALB2, or ATM germline mutations." (PMID 40830526, 2025). "This patient with BRCA2-mutated prostate cancer had a prolonged PSA response and improvement of bone metastases during 15 cycles (14 months of treatment) with ongoing PSA response when he discontinued his participation in the clinical trial and transitioned to olaparib." (PMID 41231232, 2025). "According to the European Association of Urology guidelines, which apply in Poland, it should include men from 50 years of age, men from 45 years of age and a family history of prostate cancer, men carrying BRCA2 mutations from 40 years of age, and men of African descent from 45 years of age." (PMID 39858098, 2025). "Notably, CNVs deletions involving BRCA1 exon 22 and BRCA2 exon 27 have been shown to impair homologous recombination repair, playing a significant pathogenic role in advanced prostate cancer." (PMID 40725150, 2025). "Thus, BRCA2 gene mutation is strongly associated with an increased risk of developing prostate cancer, as evidenced by the p-value (<0.0001) and corresponding confidence interval (3.487 to 32.987)." (PMID 40433050, 2025). "In pancreatic and prostate cancers, BRCA2-mutated cases achieve 7.2–8.1 months’ PFS with PARPi." (PMID 40864792, 2025). "In our observations, two male patients were treated for a prostate cancer diagnosed at an early age, which might suggest that the BRCA2-linked risk is further increased by the presence of the ATM PV." (PMID 38929805, 2024). "Consequently, it is important to consider the mutation status of BRCA2 before deciding to use PP2A activators or inhibitors to treat prostate cancer patients." (PMID 37934606, 2024). "However, from clinical data, the response rate of CDK12‐mutated prostate cancer patients to PARPi was much lower than that of patients with BRCA2 mutations." (PMID 38736108, 2024). "Contrary to current UK recommendations, both panels supported proactive conversations between primary care HCPs and patients at higher-than-average risk because of Black ethnicity, or a family history of prostate cancer, or confirmed genetic risk factors (for example, BRCA2 gene mutation)." (PMID 39038964, 2024). "In conclusion, this unicentric analysis of BRCA1/2 and HRR gene mutations in prostate cancer, analyzed over a 5-year period, found a lower prevalence of BRCA2 mutations than previously reported: only 4.9% are deemed eligible for olaparib treatment as per EMA approval." (PMID 39172235, 2024). "Male BRCA2 mutation carriers are recommended to undergo prostate cancer surveillance through measuring PSA, digital rectal exams, and prostate USG over 40 years of age, and this could also be considered for BRCA1 mutation carriers." (PMID 39590130, 2024). "Notably, the BRCA2 gene mutation was more pronounced in prostate cancer cases diagnosed in younger individuals with more severe clinical symptoms." (PMID 39364320, 2024). "As a result of the discovery that mutations in BRCA1 and BRCA2 predispose to development and aggressiveness of prostate cancer, germline testing for BRCA1, BRCA2, and other cancer predisposition syndromes such as Lynch Syndrome is likely to gain more prominence." (PMID 38583453, 2024). "Interestingly, results from the TRITON2 study (NCT02952534) showed clinical activity of rucaparib was greater in castrate-resistant prostate cancer patients with BRCA2 mutations compared to BRCA1 mutations." (PMID 38965423, 2024). "Notably, a parallel investigation in prostate cancer patients underscored the significance of BRCA2 germline mutations, particularly when associated with RB1 heterozygous deletion." (PMID 38672640, 2024).